SESN2 (sestrin 2)
Diseases named in the same sentence as SESN2 in open-access papers (continued):
Sharing a sentence is not in itself a finding about the gene and the disease.
tumor (continued). "A strong xenograft tumor formation ability was observed in shSesn2-2 expressing cells (for the summary of all tumors formed by Sesn2 knockdown cell line in two batches of nude mice)." (PMID 25962159, 2015). "Considering that the PI3K/PKB/mTOR signaling can be an important machinery for tumor cell survival and anabolic metabolism, the functional impact of SESN2 on the regulation of PTEN/PKB signaling in tumor deserves further studies." (PMID 25792980, 2015). "Recent studies have provided growing evidence that SESN2 plays a pivotal role in tumor progression." (PMID 40775338, 2025). "The effect of Sesn2 on tumor migration and invasion was also studied." (PMID 41614860, 2025). "Sesn2 has been shown to function as a tumor suppressor gene in bladder cancer and prostate cancer." (PMID 41614860, 2025). "Hypoxia, under which tumours frequently find themselves, steadily upregulates SESN2." (PMID 40361504, 2025). "Furthermore, SESN2 knockouts of these lines were significantly more sensitive to glutamine deprivation-induced cell death and formed markedly smaller tumours under inhibition of the glutamine transporter." (PMID 40361504, 2025). "Interestingly, mTORC1 activity remained elevated in tumour samples despite increased SESN2 expression." (PMID 40361504, 2025). "SESN2 functions as a tumor suppressor in many kinds of malignancies." (PMID 39388305, 2024). "Furthermore, many studies have demonstrated that a number of drugs and chemicals exert anti-tumor effects by upregulating SESN2, including but not limited to 5-fluorouracil, oxaliplatin, nelfinavir, and bortezomib." (PMID 39388305, 2024). "Sestrin 2 is a tumor biomarker that plays a key role in tumor development." (PMID 39682093, 2024). "Arguably, to pigeon-hole either SESN2 or IGF2BP3 as either as oncogene or tumor suppressor is not overly helpful unless the underlying context is considered." (PMID 37059726, 2023). "Moreover, low SESN2 expression was correlated with the characteristic of aggressive NSCLC including poor tumour differentiation, advanced TNM stage and lymph node metastasis, in contrast to high SESN2 expression." (PMID 37284849, 2023). "In most tumor-related studies, SESN2 has anticancer effects." (PMID 36980973, 2023). "Meanwhile, according to gene function analysis, SESN2 may be involved in immune responses and the tumor microenvironment (TME)." (PMID 36980973, 2023). "Since each of the tested EC cell lines represents a different stage of EC, SESN2 expression may be correlated with tumour stage and tumour metastasis." (PMID 37284849, 2023). "BA-induced SESN2 expression decreased the anti-tumor effects of BA treatment." (PMID 36611970, 2022). "However, the mechanisms by which sestrin 2 promotes tumor growth are relatively complex, especially under stress conditions." (PMID 34784907, 2021). "For diagnosis, sestrin 2 protein may be useful as an auxiliary characteristic to determine tumor classification and prognosis." (PMID 34784907, 2021). "In addition, sestrin 2 knockdown accelerated the xenograft tumor growth of HEC-1A, the CRC line SW620, and bronchial epithelial line BEAS-2B transplanted in Balb/c nude mice by targeting the mTORC1 mechanism." (PMID 34784907, 2021). "Additionally, SESN2 suppresses tumor growth by enhancing autophagy activity through the inhibition of the mTORC1 pathway." (PMID 32899752, 2020).
tumor (continued). "Moreover, the activation of Sesn2 in tumor cells can activate autophagy, which facilitates tumor cell growth under conditions of limited nutrients and oxygen." (PMID 32010489, 2020). "Decreased expression of SESN2 correlated with tumor progression." (PMID 32899752, 2020). "Therefore, we proposed that SESN1 and SESN2 are potential tumor suppressors of lung carcinogenesis as their expression appeared to be consistently downregulated in the majority of NSCLC tumors relative to control lung tissues." (PMID 31857853, 2019). "We analyzed whether inactivation of the SESN1 and/or SESN2 genes may affect cell proliferation that can be responsible for the acceleration of tumor growth." (PMID 31857853, 2019). "The findings suggested that expression of SESN2 protein may be correlated with tumor stage and tumor metastasis." (PMID 31073887, 2019). "Moreover, protein expression of SESN2 was significantly decreased in tumor tissues compared with normal tissues." (PMID 31337142, 2019). "Although our previous results shed light on a novel function of sestrin 2 as a potential tumor-suppressor gene in CRC, the exact role of sestrin 2 in CRC remains unclear." (PMID 28525387, 2017). "Western blot analysis of xenograft extracts (n = 7 mice per group) obtained at sacrifice (7 weeks after tumor cell injection) showed that the expression of sestrin 2 was significantly increased (p < 0.05) in sestrin 2-transduced cells, compared to cells transduced with empty viral vectors." (PMID 28525387, 2017). "Notably, we observed that overexpressing sestrin 2 in CRC cells implanted in nude mice reduced both the weight and the size of the resulting tumors, indicating that sestrin 2 has tumor inhibiting properties in vivo as well as in vitro." (PMID 28525387, 2017). "Moreover, knockdown of Sesn2 in BEAS-2B cells promoted the BEAS-2B cell-transplanted xenograft tumor growth in nude mice." (PMID 25962159, 2015). "Furthermore, SESN2 also plays a role in the regulation of autophagy and exhibits tumour suppressive proprieties." (PMID 22363791, 2012). "However, the same study revealed a crucial finding: Sesn2 expression in the colon epithelium is essential, as its absence compromises the colon lining, leading to increased chronic inflammation and subsequent tumour formation." (PMID 40361504, 2025). "Our recent study demonstrated that SESN1 and SESN2 might play an ambiguous role in lung carcinogenesis, supporting tumor growth at an early stage of carcinogenesis but suppressing cell proliferation and facilitating the death of tumor cells at an advanced stage." (PMID 39985075, 2025). "Notably, SESN2 expression was inhibited in PCa and may exert tumor-suppressive effects by affecting the AMPK/mTOR signaling pathway." (PMID 40775338, 2025). "Sestrin 2 is involved in many processes, such as tumor cell proliferation; apoptosis; autophagy; anoikis resistance; drug resistance; sensitivity to radiotherapy; tumor differentiation; tumor, node, and metastasis (TNM) staging; lymphatic metastasis; and patient survival." (PMID 34784907, 2021). "Because Sesn2 can suppress TORC1 activation, Sesn2 may confer tumor suppressor activity." (PMID 32010489, 2020). "Therefore, the altered stressful tumor microenvironment and indicated changes of transcriptional regulators may possibly account for the increased SESN2 expression after sorafenib treatment in HCC, which need further investigations in the future." (PMID 30311444, 2018). "Moreover, SESN2 acts as an important contributor in autophagy induction and tumor suppression." (PMID 28118855, 2017). "Our findings demonstrate that Sesn2 functions as an oncogene in OSCC, promoting tumor progression by modulating the PI3K/AKT/mTOR and MAPK signaling pathways, suggesting its potential as a therapeutic target for OSCC." (PMID 41614860, 2025).
tumor (continued). "Conversely, in tumor cells with MTDH KD, the binding of SND1 to SESN2 was notably weakened, indicating the crucial role of MTDH in promoting the SND1-SESN2 interaction." (PMID 40775338, 2025). "These attributes render Sesn2 a compelling candidate for in-depth investigation in OSCC, with the potential to clarify its precise impact on tumor progression and to identify novel therapeutic targets." (PMID 41614860, 2025). "Sestrin-2 is a stress-induced protein that enhances LKB1-dependent activation of AMPK, functioning as a tumor suppressor in NSCLC." (PMID 38396629, 2024). "SESN2 and AIFM2 are responsible for tumor cell survival, but their exact functions in AML cells ferroptosis remains uncharacterized." (PMID 34784264, 2022). "To better understand the link between the inactivation of Sesn2 and suppression of tumor growth, we hypothesized that the positive impact of Sesn2 on tumor growth could be mediated by the activation of AKT kinase as the deficiency of Sesn2 might downregulate AKT activity required for tumor growth." (PMID 31857853, 2019). "Although inactivation of Sesn2 in mice led to inhibition of tumor growth, inactivation of either SESN1 or SESN2 in A549 cells stimulated cell proliferation and protected cells against cell death induced by glucose starvation." (PMID 31857853, 2019). "Chen et al23 reported that SESN2 expression markedly declined in HCC tissues in comparison to normal liver tissues, indicating its tumor suppressive role." (PMID 30311444, 2018). "Colorectal cancer tumor growth and metastasis was found to be enhanced by increased levels of oncogenic piR-1245 which is capable of binding and subsequently suppressing multiple tumor suppressors such as ATF3, DUSP1, and SESN2 by degradation of mRNA." (PMID 33673453, 2021). "Importantly, PTEN nuclear translocation promotes autophagy through activation of the p-Jun-SESN2-AMPK pathway in A549 and HeLa cells tumor cells, supporting SESNs as potential synergistic targets in therapies against PTEN-null tumors." (PMID 31546746, 2019). "Inactivation of Sesn1 has no additional effects on tumor growth and the lifespan of Sesn2-/-;KrasLSL-G12D mice." (PMID 31857853, 2019). "Accordingly, we demonstrated that the inactivation of the SESN1 and/or SESN2 genes by the CRISPR/Cas9 system accelerates cell proliferation in A549 cells and this mechanism may be responsible for tumor growth." (PMID 31857853, 2019). "Although we did not observe a significant change in tumor volume (data not shown), we unintentionally found higher expression of SESN2 and SESN3 in intratumoral NK-92 cells than those in splenic and peritoneal NK-92 cells." (PMID 29163816, 2017). "Most strikingly, the Sesn2 knockout mouse presented no tumor formation, even no obvious shorted lifespan which is in contrast to its roles in tumor suppression and antiaging demonstrated previously." (PMID 25962159, 2015). "Taken together, our results indicate that knockdown of Sesn2 promotes malignant transformation of BEAS-2B cells both in vitro and in vivo, and Sesn2 may act as a potential tumor suppressor in lung epithelial cells." (PMID 25962159, 2015). "Consequently, we hypothesized that SESN2 may exert a tumor-suppressive role in PCa and that the MTDH-SND1 complex targets SESN2 mRNA for degradation, thereby promoting PCa progression." (PMID 40775338, 2025). "However, some other studies postulated higher SESN2 expression levels in tumor tissue compared to adjacent non-cancerous tissue were partially associated with poor outcomes for patients with lung, endometrial and hepatocellular cancer." (PMID 36611970, 2022). "The relevance of SESN2 for tumor response to chemo- or radiotherapy is not clear." (PMID 36611970, 2022).
tumor (continued). "Therefore, Sesn2 has a positive impact on lung tumor growth during early steps of carcinogenesis but does not affect the life expectancy of tumor-bearing mice." (PMID 31857853, 2019). "Thus, the role of sestrin 2 in CRC might be strengthened by its ability to restrict cell proliferation, therefore preventing tumor expansion and invasion." (PMID 28525387, 2017). "Finally, the potential manner by which SESN2 influences the tumor microenvironment in HCC has not yet been explored." (PMID 28118855, 2017). "Thus, low expression of SESN2 in CRC may increase oxidative stress and aggravate tumour metastasis." (PMID 37284849, 2023). "They hypothesized that certain levels of SESN2 expression during the early steps of carcinogenesis might be required to support the activity of AKT kinase, the critical positive regulator of glucose transport, anabolism and cell viability that contribute to growth and proliferation of tumour cells." (PMID 37284849, 2023). "Moreover, further analysis of the A375 tumors treated with A922500 revealed increased SESN2, SOD1, and SOD2 expression, concomitant with increased lipid peroxidation, confirming that our A922500 administration had been effective in inducing ROS and NRF2 signaling in tumor cells in vivo." (PMID 35732120, 2022). "Nevertheless, certain levels of SESN2 expression during early steps of carcinogenesis might be required to support the activity of AKT kinase, the critical positive regulator of glucose transport, anabolism, and cell viability that contributes to growth and proliferation of tumor cells." (PMID 31857853, 2019). "Therefore, it is worth further investigating whether or not insulin could play a role in regulating SESN2 content in vivo and its pathological significance in a variety of metabolic and tumor diseases." (PMID 25792980, 2015). "Tumor weight, also recorded at sacrifice 7 weeks after SW620 cell injection, was significantly lower (p < 0.05) in sestrin 2-overexpressing xenografts compared with negative controls." (PMID 28525387, 2017).
cardiovascular diseases (13 papers, 2014 to 2025). "This study examines the association between serum Sestrin2 (SESN2) levels and cardiovascular disease (CVD) risk factors in healthy and diabetic adults, using data from the Qatar Biobank (QBB)." (PMID 39636755, 2025). "Our current findings add weight to the theory that SESN2 levels are reduced as the disease advances, especially in the context of risk factors associated with cardiovascular disease." (PMID 39769227, 2024). "The expression of SESN2 decreases with age and its levels are associated with cardiovascular disease and many age-related pathologies." (PMID 36902310, 2023). "Our study implies that stimulating expression of SESN2 might be an effective pharmacological target for treatment of AngII-associated cardiovascular diseases." (PMID 24838122, 2014). "Our results indicate that the induction of SESN2 acts as a compensatory response to AngII for survival, implying that stimulating expression of SESN2 might be an effective pharmacological target for the treatment of AngII-associated cardiovascular diseases." (PMID 24838122, 2014). "Data obtained from animal models indicate that Sesn2 is a promising target for the treatment of cardiovascular diseases in human patients." (PMID 32010489, 2020). "We therefore believe that microRNA-122 and Sestrin-2 can be developed as potential therapeutic targets against apoptosis in cardiovascular diseases." (PMID 35540851, 2018). "Taken together, SESN2 might be a beneficial target for amelioration of cardiovascular diseases, indicating its potential therapeutic role in cardiovascular diseases." (PMID 31867002, 2019). "Therefore, Sesn2 can activate downstream AMPK and inhibit mTOR signal to induce autophagy, so as to regulate the occurrence and development of cardiovascular diseases, suggesting that Sesn2 may be a pharmacological target for treating cardiovascular diseases." (PMID 37063954, 2023). "Taken together, SESN2 may represent a biomarker of the extent of CHF and a novel target for the amelioration of cardiovascular diseases." (PMID 33942488, 2021).
neurodegenerative disease (8 papers, 2016 to 2025). A disorder of the central nervous system characterized by gradual and progressive loss of neural tissue and neurologic function. "Furthermore, SESN2 may inhibit the production of ROS and produce antioxidant effects, making it a potential target for the treatment of AD and neurodegenerative diseases, as AD neuronal death is likely caused by oxidative damage." (PMID 36467613, 2022). "We investigated the potential of SESN2 as a new neuroprotective target and examined its relationship with PDEIs, which are known for their protective effects in neurodegenerative diseases." (PMID 40842769, 2025). "Sestrin2 (Sesn2) exerts neuroprotective properties in some neurodegenerative diseases." (PMID 27453548, 2016). "Some scholars reported that the depletion of KDM1A increased the expression level of sestrin-2 (SESN2) and then resulted in the inhibition of mTOR complex 1 (mTORC1), which was good for sustainability of cellular homeostasis and was a protective mechanism against neurodegenerative diseases." (PMID 33987474, 2020).
metabolic disorders (7 papers, 2020 to 2024). "SESN2 plays a key role in maintaining metabolic homeostasis in animals and preventing various diseases caused by metabolic disorders." (PMID 35954183, 2022). "Our study contributes to the growing body of evidence linking SESN2 to cellular stress responses in the context of metabolic disorders." (PMID 39769227, 2024). "Sesn2 provides a novel therapeutic target for the prevention of age-related diseases and metabolic disorders." (PMID 32010489, 2020).
infection (6 papers, 2020 to 2025). The state of being infected such as from the introduction of a foreign agent such as serum, vaccine, antigenic substance or organism. "Transcriptional analysis indicated infection-specific up-regulation of genes associated with glucose starvation, such as SESN2 that encodes for stress-inducible metabolic regulator Sestrin2." (PMID 34710198, 2021). "This elevation could be associated with acute infection and cellular stress, which is known to upregulate Sestrin-2 expression." (PMID 38715114, 2024). "Through in vivo and in vitro experiments, we confirmed that SESN2 could inhibit this “infection” through the reduction of exosome release by promoting autophagic degradation; Rab-7a-mediated autophagosome and lysosome fusion and TFEB-mediated lysosomal function repair may play roles in this process." (PMID 40612680, 2025). "Interestingly, the levels of the CHOP (DDIT3), DR5 (TNFRSF10B), ATF3, and SESN2 proteins were dramatically increased in CYB5R3-overexpressing H1299 and H1703 cells following Ad-CYB5R3 infection." (PMID 38253797, 2024). "While the expression of these cytoprotective genes, which are crucial for the defense against oxidative stress, was not altered, the antioxidant gene Sestrin2 (SESN2) was significantly upregulated after infection." (PMID 33121145, 2020).
adenocarcinoma (3 papers, 2015 to 2020). A common cancer characterized by the presence of malignant glandular cells. "To analyze whether SESN2 plays a role in the regulation of mitochondrial respiration in adenocarcinoma A549 cells, we analyzed the levels of basal and maximal respiration in control and SESN2 knockout cells where expression SESN2 was inactivated with two different sgRNA." (PMID 32287270, 2020). "In this work, we extended our previous observation using cSesn-negative C. elegans and SESN2-null adenocarcinoma A549 cells as alternative models to demonstrate that inactivation of sestrins decreases mitochondrial respiration rate." (PMID 32287270, 2020).
kidney disease (2 papers, 2022 to 2025). "This suggests the existence of a new signaling pathway, SESN2/AMPK/KIM-1, offering a novel perspective on the mechanism of S-PPE NP therapy for kidney disease." (PMID 40485171, 2025).